HLA-DQB2 (major histocompatibility complex, class II, DQ beta 2)
Description:
Binds peptides derived from antigens that access the endocytic route of antigen presenting cells (APC) and presents them on the cell surface for recognition by the CD4 T-cells. The peptide binding cleft accommodates peptides of 10-30 residues. The peptides presented by MHC class II molecules are generated mostly by degradation of proteins that access the endocytic route, where they are processed by lysosomal proteases and other hydrolases. Exogenous antigens that have been endocytosed by the APC are thus readily available for presentation via MHC II molecules, and for this reason this antigen presentation pathway is usually referred to as exogenous. As membrane proteins on their way to degradation in lysosomes as part of their normal turn-over are also contained in the endosomal/lysosomal compartments, exogenous antigens must compete with those derived from endogenous components. Autophagy is also a source of endogenous peptides, autophagosomes constitutively fuse with MHC class II loading compartments. In addition to APCs, other cells of the gastrointestinal tract, such as epithelial cells, express MHC class II molecules and CD74 and act as APCs, which is an unusual trait of the GI tract. To produce a MHC class II molecule that presents an antigen, three MHC class II molecules (heterodimers of an alpha and a beta chain) associate with a CD74 trimer in the ER to form a heterononamer. Soon after the entry of this complex into the endosomal/lysosomal system where antigen processing occurs, CD74 undergoes a sequential degradation by various proteases, including CTSS and CTSL, leaving a small fragment termed CLIP (class-II-associated invariant chain peptide). The removal of CLIP is facilitated by HLA-DM via direct binding to the alpha-beta-CLIP complex so that CLIP is released. HLA-DM stabilizes MHC class II molecules until primary high affinity antigenic peptides are bound. The MHC II molecule bound to a peptide is then transported to the cell membrane surface. In B-cells, the interaction between HLA-DM and MHC class II molecules is regulated by HLA-DO. Primary dendritic cells (DCs) also to express HLA-DO. Lysosomal microenvironment has been implicated in the regulation of antigen loading into MHC II molecules, increased acidification produces increased proteolysis and efficient peptide loading.
Synonyms: HLA-DXB; DQB2; HLA-DQB1
Tractability: Antibody: UniProt places it where antibodies can reach, with high confidence; its Gene Ontology location is reachable by antibodies, with high confidence; UniProt predicts a signal peptide or a membrane-spanning region. PROTAC: ubiquitination databases record sites on it.
Gene: Protein-coding gene on chromosome 6 (32,756,094 to 32,763,543, reverse strand). Ensembl gene ENSG00000232629.
Subcellular location: Cell membrane; Endoplasmic reticulum membrane; Golgi apparatus, trans-Golgi network membrane; Endosome membrane; Lysosome membrane
Pathways (Reactome):
Immune System: Co-inhibition by PD-1; Downstream TCR signaling; Generation of second messenger molecules; Interferon gamma signaling; MHC class II antigen presentation; Phosphorylation of CD3 and TCR zeta chains; Translocation of ZAP-70 to Immunological synapse
Gene Ontology:
Molecular function: MHC class II protein complex binding; MHC class II receptor activity; peptide antigen binding
Biological process: antigen processing and presentation of exogenous peptide antigen via MHC class II; immune response; peptide antigen assembly with MHC class II protein complex; positive regulation of immune response; positive regulation of T cell activation; antigen processing and presentation
Cellular component: clathrin-coated endocytic vesicle membrane; endocytic vesicle membrane; ER to Golgi transport vesicle membrane; Golgi membrane; late endosome membrane; lumenal side of endoplasmic reticulum membrane; lysosomal membrane; MHC class II protein complex; plasma membrane; trans-Golgi network membrane; transport vesicle membrane; endoplasmic reticulum membrane; endosome membrane; Golgi apparatus; membrane
Genetic constraint (gnomAD): Loss-of-function variants: 21 observed, 20.91 expected, observed/expected ratio (o/e) 1, 90% interval 0.71 to 1.45. The upper end of that interval is the gene's LOEUF score, 1.45, which puts it in group 5 of 6, group 1 being the genes least tolerant of losing a copy. Missense variants: 265 observed, 277.26 expected, observed/expected ratio (o/e) 0.96, 90% interval 0.86 to 1.06. Synonymous variants: 103 observed, 110.86 expected, observed/expected ratio (o/e) 0.93, 90% interval 0.79 to 1.09.
Homologues: Orthologues: chimpanzee HLA-DQB2 (98% identical), guinea pig HLA-DQB2 (76% identical), rat RT1-Bb (75% identical), mouse H2-Ab1 (72% identical), dog HLA-DQB2 (51% identical). Paralogues in human: HLA-DQB1 (78% identical), HLA-DRB5 (65% identical), HLA-DRB1 (64% identical), HLA-DPB1 (60% identical), HLA-DOB (55% identical), HLA-DOA (22% identical), HLA-DQA1 (22% identical), HLA-DPA1 (21% identical), HLA-DQA2 (21% identical), HLA-DRA (21% identical), HLA-DMB (19% identical), HLA-DMA (16% identical), and 1 more.
Diseases named in the same sentence as HLA-DQB2 in open-access papers:
HLA-DQB2 is named in the same sentence as 29 diseases in open-access papers, as found by Europe PMC text mining. Sharing a sentence is not in itself a finding about the gene and the disease. The quoted sentences say what the papers report.
autoimmune disease (3 papers, 2018 to 2024). A disorder resulting from loss of function or tissue destruction of an organ or multiple organs, arising from humoral or cellular immune responses of the individual to their own tissue constituents. "Increased HLA-DQB2 expression has been associated with susceptibility to the autoimmune disease rheumatoid arthritis and increased renal transplant rejection." (PMID 35844512, 2022). "Within this chromosome, HLA-DQA1, HLA-DRB6, HLA-DQA2, HLA-DQB2, HLA-DRB1, and HLA-DQB1-AS1 were notable for having causal associations among several autoimmune diseases." (PMID 39590325, 2024).
breast carcinoma (3 papers, 2021 to 2024). "HLA-DQB2 has been shown to be highly expressed in breast cancer and predicts better overall survival." (PMID 38420434, 2024). "Finally, we found three PGx-eQTL genes that were shared between our breast cancer GWAS and the GWAS catalog traits of cancer and hormone levels, namely SNX13, HLA-DQB2, and MORF4L1." (PMID 38965614, 2024).
lung carcinoma (2 papers, 2021 to 2024). "Currently, there is no definitive study on the relationship between HLA-DRB9, HLA-DQB2 and lung cancer, and further verification will be needed." (PMID 34938740, 2021).
multiple sclerosis (2 papers, 2017 to 2019). A progressive autoimmune disorder affecting the central nervous system resulting in demyelination. "Gene regions spanning the identified four-SNP signature, HLA-DQB2, MBP, UVRAG, and ZAK(CDCA7), are known to be related to either the MoA of Copaxone or the pathophysiology of multiple sclerosis: HLA-DQB2 is involved in antigen processing and presentation, central to Copaxone’s MoA." (PMID 28569182, 2017).
asthma (1 paper, 2022). "These analyses indicate that the most significant asthma locus in AOA is due to variation in two credible sets, whose effects are likely attributable to their impact on expression of the HLA-DQA2 and HLA-DQB2 genes and of the HLA-DQA1*03:01 allele." (PMID 35606880, 2022). "While previous asthma GWAS have implicated the classical and highly polymorphic HLA-DQA1 and HLA-DQB1 class II genes, our study revealed associations with HLA-DQA2 and HLA-DQB2 genes in risk for AOA." (PMID 35606880, 2022).
Cognitive impairment (1 paper, 2025). Abnormal cognition is characterized by deficits in thinking, reasoning, or remembering. "The rs9276572(C) HLA-DQB2 polymorphism requires further study as a new potential marker of immunological disorders, morphometric changes in the brain, and cognitive impairment in schizophrenia." (PMID 40416497, 2025). "The rs9276572(C) polymorphism of HLA-DQB2 requires further study as a new potential marker of immunological disorders, morphometric changes in the brain and cognitive impairment in schizophrenia." (PMID 40416497, 2025).
COVID-19 (1 paper, 2021). A disease caused by infection with severe acute respiratory syndrome coronavirus 2. "There was also significant upregulation of MHC-II expression (HLA-DRB5, HLA-DQB2, HLA-DPB1, etc.) in mild COVID-19 patients." (PMID 33473155, 2021).
cutaneous melanoma (1 paper, 2019). A primary melanoma arising from atypical melanocytes in the skin. "The expressions of most HLA class II genes were significantly up-regulated in cutaneous melanoma, except HLA-DQB2, which was significantly down-regulated in cutaneous melanoma compared to normal skin tissues." (PMID 31212865, 2019).
IgA nephropathy (1 paper, 2015). "The intergenic region between HLA-DQB1 and HLA-DQB2 was linked to IgA nephropathy in one GWAS study; but to date no epidemiologic study has linked IgA nephropathy to kidney malignancy." (PMID 25784652, 2015).
lung squamous cell carcinoma (1 paper, 2024). "For lung squamous cell carcinoma, 11 genes were causally related, comprising COPA, NCSTN, U91328.19, GABBR1, IER3, HLA-DQB1-AS1, HLA-DQB2, ANKRD26, PKD2L1, PSMA4 and RAD51C." (PMID 38834983, 2024). "For lung squamous cell carcinoma, 9 genes were causally related, comprising U91328.19, FLOT1, LINC00243, HLA-DQA1, HLA-DQB1, HLA-DQB1-AS1, HLA-DQB2, ZNF483 and BLOC1S2." (PMID 38834983, 2024).
periodontitis (1 paper, 2021). An acute or chronic inflammatory process that affects the tissues that surround and support the teeth. "Almost all the HLA genes were significantly upregulated in periodontitis, except for HLA-DQB2 which showed a significantly lower expression." (PMID 34285922, 2021).
Sepsis (1 paper, 2023). Sepsis is defined as life-threatening organ dysfunction caused by a dysregulated host response to infection. "In this study, the key genes downregulated during sepsis also encoded proteins responsible for the immune response, including the expression of antigen-presenting cells, the regulation of cytokine production, and the activation of B and T lymphocytes (i.e., CD79A, HLA-DQB2, PLD4, and CCR7)." (PMID 37298316, 2023). "In addition, we identified key genes that were upregulated in sepsis, namely, S100A8, S100A9, and CR1, as well as those that were downregulated, namely, CD79A, HLA-DQB2, PLD4, and CCR7." (PMID 37298316, 2023).
tumor (7 papers, 2021 to 2025). "The expression of HLA-F was downregulated in the high-risk group, whereas, the expression of HLA-DQB2 was upregulated in the high-risk group, indicating that this possibly led to tumor immune evasion (P-value < 0.05)." (PMID 35144613, 2022). "Two genes related to a favourable immune response, ARG1 and HLA-DQB2, and the tumour markers CDKN2A and KRT7 were selected for validation with qPCR and further analysis." (PMID 39712018, 2024). "HLA-C, which belongs to HLA-I and can present endogenous tumor antigens to kill tumor cells effectively, was less expressed in the high-risk group, while HLA-II, such as HLA-DPB2, HLA-DQB2, HLA-DOA, and HLA-DQA2, showed an increase in the high-risk group." (PMID 35754846, 2022). "A next-generation sequencing transcriptomic immune profile analysis applied to 28 persistent CIN3 lesions and 14 normal biopsies identified four genes, the immune markers ARG1 and HLA-DQB2 and the tumour markers CDKN2A and KRT7, as possible markers for differentiating between CIN3 and normal tissue." (PMID 39712018, 2024). "The results showed that, with the exception of SMIM24, which was highly expressed in normal tissues, PLCB2, HLA-DQB2, IFNG, and XCR1 were all highly expressed in tumor tissues." (PMID 39273185, 2024). "However, cDCs in the PI3K/mTORi+PD‐1i‐treated tumours upregulated expression of genes related to antigen presentation via major histocompatibility complex class II (MHC II) (HLA‐DRB1, HLA‐DQB1, HLA‐DPB1, HLA‐DQB2, CD74) compared with cDCs in tumours treated with PD‐1i, PI3K/mTORi‐ or vehicle." (PMID 38711203, 2024).
cancer (5 papers, 2019 to 2025). A tumor composed of atypical neoplastic, often pleomorphic cells that invade other tissues. "Genes such as human leukocyte antigen (HLA) complex genes HLA-DQA2/HLA-DQB2 encoding HLA-Class II molecules, cancer/testis (CT) antigen XAGE1B and FOLR genes, which are related to multiple cancers, were steadily upregulated in advanced stage." (PMID 33000418, 2021). "Yin and colleagues stratified BC patients into high and low risk cancers based on a seven gene expression assay (BATF, CD3D, HLA-DQB2, JUN, MAP2K6, NFKBIE, PAK1)." (PMID 40148963, 2025).
infection (2 papers, 2022 to 2024). The state of being infected such as from the introduction of a foreign agent such as serum, vaccine, antigenic substance or organism. "Among these genes, the partial control of human leucocyte antigen (HLA) genes like HLA-DQB2 on immune response to infection could be used as a reasonable therapeutic target, which will be further explored to revive the antitumor immunity in ALL." (PMID 36340735, 2022).
HLA-DQB2 also shares sentences with these, for which no sentence is quoted: rheumatoid arthritis (3 papers); cardiovascular disease (1); Crohn disease (1); glioma (1); hepatitis B (1); influenza (1); lymphoma (1); Obesity (1); primary immunodeficiency (1); sarcopenia (1); schizophrenia (1); tuberculosis (1); Type-1 diabetes (1); ulcerative colitis (1).